SLC39A1 (solute carrier family 39 member 1)
Description:
Transporter for the divalent cation Zn(2+). Mediates the influx of Zn(2+) into cells from extracellular space. Functions as the major importer of zinc from circulating blood plasma into prostate cells.
Synonyms: ZIP1; ZIRTL
Tractability: Antibody: UniProt places it where antibodies can reach, with high confidence; its Gene Ontology location is reachable by antibodies, with high confidence; UniProt predicts a signal peptide or a membrane-spanning region.
Gene: Protein-coding gene on chromosome 1 (153,959,099 to 153,968,667, reverse strand). Ensembl gene ENSG00000143570.
Subcellular location: Cell membrane; Endoplasmic reticulum membrane
Pathways (Reactome):
Transport of small molecules: Zinc influx into cells by the SLC39 gene family
Gene Ontology:
Molecular function: protein binding; zinc ion transmembrane transporter activity; transmembrane transporter activity; metal ion transmembrane transporter activity; signaling receptor binding
Biological process: zinc ion transmembrane transport; monoatomic cation transport; zinc ion import across plasma membrane; metal ion transport; transmembrane transport
Cellular component: endoplasmic reticulum membrane; plasma membrane; membrane
Genetic constraint (gnomAD): Loss-of-function variants: 17 observed, 21 expected, observed/expected ratio (o/e) 0.81, 90% interval 0.55 to 1.21. The upper end of that interval is the gene's LOEUF score, 1.21, which puts it in group 5 of 6, group 1 being the genes least tolerant of losing a copy. Missense variants: 343 observed, 417.94 expected, observed/expected ratio (o/e) 0.82, 90% interval 0.75 to 0.9. Synonymous variants: 183 observed, 196.42 expected, observed/expected ratio (o/e) 0.93, 90% interval 0.82 to 1.05.
Homologues: Orthologues: chimpanzee SLC39A1 (99% identical), macaque SLC39A1 (99% identical), rabbit SLC39A1 (97% identical), dog SLC39A1 (96% identical), pig SLC39A1 (95% identical), guinea pig SLC39A1 (95% identical), rat Slc39a1 (94% identical), mouse Slc39a1 (94% identical), tropical clawed frog slc39a1 (50% identical), Caenorhabditis elegans zipt-2.1 (29% identical), Caenorhabditis elegans zipt-2.2 (25% identical). Paralogues in human: SLC39A2 (34% identical), SLC39A3 (31% identical).
Diseases named in the same sentence as SLC39A1 in open-access papers:
SLC39A1 is named in the same sentence as 63 diseases in open-access papers, as found by Europe PMC text mining. Sharing a sentence is not in itself a finding about the gene and the disease. The quoted sentences say what the papers report.
prostate carcinoma (36 papers, 2005 to 2025). A carcinoma that arises from epithelial cells of the prostate gland. "Down-regulation of SLC39A1 expression has been associated with prostate cancer pathogenesis and is linked to poor prognosis, with most studies focusing on zinc’s direct effects on apoptosis or cell growth inhibition." (PMID 40355755, 2025). "Studies have shown that SLC39A1 is overexpressed in prostate cancer, causing depletion of zinc in the glands." (PMID 36290667, 2022). "Overexpression of miR-183-96-182 with Zn deficiency in food and SLC39A1 down-regulation directly leads Zn loss in prostate and upregulate the risk for prostate cancer." (PMID 33535184, 2021). "Two of the affected genes, MFSD2A and SLC39A1 have been reported as tumor suppressor genes in lung and prostate cancer, respectively, which by definition could carry mutations through the entire length." (PMID 28410231, 2017). "Our discovery of significant interactions between SLC39A1 and genes related to citrate metabolism, notably SLC25A1, suggests potential new therapeutic targets for further investigation in the context of prostate cancer and other SLC39A1-related disorders." (PMID 40355755, 2025). "While we were unable to fully elucidate the mechanism behind the positive effects of SLC39A1 knockout on cell growth, the downregulation of SLC39A1 has been observed in prostate cancer." (PMID 40355755, 2025). "This metabolic profile aligns with a role of SLC39A1-KO in mitochondrial function, possibly through zinc-dependent inhibition of mitochondrial aconitase, as previously reported for prostate cancer cells." (PMID 40355755, 2025). "In contrast with its oncogenic role in gastric cancer and glioma, SLC39A1 has been shown to exert tumor suppression effects in prostate cancer." (PMID 36407082, 2022). "Ectopic expression of SLC39A1 suppressed nuclear factor-κB (NF-κB) in prostate cancer cells in vitro and in vivo and consequently upregulated expression of pro-angiogenic and pro-metastatic cytokines." (PMID 34615436, 2021). "It has been found that SLC39A1 act as a significant role in prostate cancer, breast cancer, and colorectal cancer." (PMID 34615436, 2021). "Kolenko and his colleagues have reported that the decline of Zn in tumor tissues and serum of patients with prostate carcinoma, as well as decreased expression of SLC39A1, 2, and 3 has been detected." (PMID 33535184, 2021). "Several researchers have observed the dysregulated expression of SLC39A1 in prostate cancer, breast cancer, and colorectal cancer, while the differentiated expression in normal liver and EHCC tissues has not been summarized." (PMID 34615436, 2021). "Studies have reported that SLC39A1 were expressed in prostate cancer and gastric cancer, which leaded zinc was depleted in adenocarcinomatous glands." (PMID 32744318, 2020). "Low levels of Zn have been detected in serum and tumor tissues of patients with prostate cancer, and downregulated expression of SLC39A1, SLC39A2 and SLC39A3 has been demonstrated." (PMID 32744318, 2020). "The distinct role of SLC39A1 in prostate cancer may be partially explained by the fact that the prostate gland contains extremely high zinc levels and evolves with unique functions." (PMID 36407082, 2022). "Besides prostate cancer, the function of SLC39A1 seems controversial in hepatocellular carcinoma (HCC)." (PMID 36407082, 2022). "SLC39A1 was reduced and inhibited tumor progression in prostate cancer." (PMID 36407113, 2022). "Additional mechanisms of SLC39A1 participating in prostate cancer are also possible." (PMID 34615436, 2021). "SLC39A1 regulates the malignant potential of prostate cancer cells by inhibiting the nuclear factor kappa B (NF-κB) signaling pathway, and SLC39A1 may play a role as a tumor suppressor gene in prostate cancer." (PMID 32461965, 2020). "SLC39A1 is a zinc ion transport protein which inhibits the progression of prostate cancer." (PMID 33292262, 2020).
prostate carcinoma (continued). "Low expression of SLC39A1 decreases the level of Zn2+ in prostate cancer tissue, thereby reducing the level of citrate, and ultimately resulting in the malignant progression of prostate cancer." (PMID 33292262, 2020). "Therefore, we propose that ZIP1 (SLC39A1) can be described as a tumor suppressor gene in prostate cancer." (PMID 16700911, 2006). "SLC39A1 could significantly decreased the level of Zn2 + in cancer tissue, thereby reducing the level of citrate, and ultimately resulting in the malignant progression of prostate cancer and glioma." (PMID 36307882, 2022). "Recent studies have suggested that low SLC39A1, SLC39A2 and SLC39A3 expression in prostate cancer, low SLC39A3 and high SLC39A4 expression in pancreatic cancer." (PMID 34615436, 2021). "miR-96 is over-expressed in prostate cancer cells and was found to promote prostate cancer cell proliferation by suppressing FOXO1 and SLC39A1." (PMID 25333253, 2014).
glioma (12 papers, 2020 to 2025). A benign or malignant brain and spinal cord tumor that arises from glial cells (astrocytes, oligodendrocytes, ependymal cells). "SLC39A1 is negatively correlated with NK cell activation and monocytes in gliomas and B‐cell immunity in Pan‐Cancer, contributing to tumour immune evasion and NK cell‐mediated cytotoxicity suppression." (PMID 40462487, 2025). "The analysis of bioinformatics data indicated that SLC39A1 expression was increased in glioma samples and that higher SLC39A1 levels were predictive of poorer survival rates." (PMID 37298344, 2023). "The in vitro experimental findings showed that SLC39A1 increased glioma cell proliferation, inhibiting apoptosis, and is possibly linked to the upregulation of MMP2/MMP9." (PMID 37298344, 2023). "Univariate and multivariate analyses indicated that SLC39A1 was an independent indicator of unfavorable glioma prognosis." (PMID 37298344, 2023). "Recently, Wang's study revealed that SLC39A1 was highly expressed in gliomas and negatively correlated with glioma outcome, highlighting its involvement in different malignancies." (PMID 36407082, 2022). "Slc39a1 is a zinc ion transport protein related to the progression of glioma by promoting MMP2 and MMP9, and is increased in the progression of schizophrenia." (PMID 36614117, 2022). "Recently, hyper-expression of SLC39A1 has been reported to participate in the malignant progression of hepatocellular carcinoma and glioma." (PMID 36407082, 2022). "Of note, involvement of SLC39A1 in modulating infiltration of immune cells was also suggested in glioma microenvironment." (PMID 36407082, 2022). "In the meantime, we used a CCK-8, flow cytometer, RT-qPCR, western blot, and other technologies to analyze the correlation between SLC39A1 and glioma proliferation and apoptosis in vitro, and the expression of invasion-related MMP2\MMP9 proteins." (PMID 33292262, 2020). "The TCGA, CCGA, GSE16011, GSE44971 and GSE11260 data sets were employed to evaluate the expression level of SLC39A1 in paracancerous and glioma tissues." (PMID 33292262, 2020). "In this study, we used TCGA, CGGA, and GEO databases to comprehensively analyze the expression of SLC39A1 and its role in the prognosis of glioma patients." (PMID 33292262, 2020). "Univariate and multivariate analysis show that SLC39A1 independently indicated poor prognosis in patients with gliomas." (PMID 33292262, 2020). "CCK-8 and flow cytometry results show that SLC39A1 promotes proliferation of glioma cells and inhibits their apoptosis; RT-qPCR and western blot results show that SLC39A1 promotes the progression of glioma by increasing the expression level of MMP2\MMP9." (PMID 33292262, 2020). "In order to study the role of SLC39A1 in gliomas, we stably silenced or overexpressed SLC39A1 by transfecting SLC39A1 siRNA or SLC39A1 overexpression plasmid." (PMID 33292262, 2020). "The results showed that the expression of SLC39A1 was significantly higher in gliomas than in paracancerous tissues." (PMID 33292262, 2020). "The findings in this report reveal the important role and mechanism of SLC39A1 in the progression of gliomas, and this report also analyzes the correlation between SLC39A1 and immune cell infiltration in the glioma microenvironment." (PMID 33292262, 2020). "The CGGA database samples were divided into high and low expression groups using the median of SLC39A1 expression according to the results of glioma mRNA sequencing." (PMID 33292262, 2020). "We employed the TCGA and CGGA databases to study the role of SLC39A1 in the prognosis of glioma patients." (PMID 33292262, 2020). "By studying the role and mechanism of SLC39A1 in the progression of gliomas, perhaps a new therapeutic target can be provided for their treatment." (PMID 33292262, 2020). "The results showed that in the three data sets, SLC39A1 expression in gliomas was significantly higher than in the paracancerous tissues, consistent with the analysis results from the TCGA data set." (PMID 33292262, 2020).
glioma (continued). "In conclusion, our study shows that SLC39A1 plays an important role in the malignant progression of gliomas." (PMID 33292262, 2020). "In vitro experimental results show that SLC39A1 promotes proliferation of glioma cells, inhibits their apoptosis, and promotes expression of MMP2\MMP9." (PMID 33292262, 2020). "In order to study the relationship between SLC39A1 expression and clinicopathological parameters, we downloaded clinical data for 1018 gliomas from CGGA." (PMID 33292262, 2020). "Since the prognosis of glioma patients is affected by a variety of clinicopathological factors, in order to further evaluate the prognostic value of SLC39A1 in glioma patients in the CGGA database, we used cox regression analysis." (PMID 33292262, 2020). "A recent study has also revealed the crucial role of SLC39A1 in the development of gliomas." (PMID 37298344, 2023). "It has also been reported that SLC39A1 is highly expressed in glioma tissue, which can promote the proliferation of tumor cells, inhibit apoptosis, and affect the level of immune infiltration in the glioma microenvironment." (PMID 37239411, 2023). "SLC39A1 shows promise as a novel prognostic biomarker and therapeutic target for gliomas." (PMID 38053842, 2023). "Besides, SLC39A1 promotes the proliferation of glioma cells, inhibits their apoptosis, and promotes the expression of MMP2 & MMP9." (PMID 34615436, 2021). "The TCGA database was used to analyze the expression of SLC39A1 in gliomas." (PMID 33292262, 2020). "This suggests that SLC39A1 may be related to the proliferation, metastasis and invasion ability of gliomas." (PMID 33292262, 2020). "Bioinformatic analysis shows that SLC39A1 expression is up-regulated in glioma tissues." (PMID 33292262, 2020). "In this study, K-M survival analysis, univariate Cox analysis, multivariate Cox analysis, ROC curve analysis, and other methods are employed, using the TCGA, GEO and CCGA databases, to show that SLC39A1 independently indicated poor prognosis in patients with gliomas." (PMID 33292262, 2020). "In vitro experimental results show that SLC39A1 promotes the proliferation of glioma cells and inhibits their apoptosis, and may be related to MMP2\MMP9 up-regulation." (PMID 33292262, 2020). "Multivariate cox analysis showed that SLC39A1 might be an independent factor affecting the prognosis of patients with glioma (HR = 1.456; 95% CI 1.253–1.692; P < 0.001)." (PMID 33292262, 2020). "SLC39A1 may serve as a new prognostic biomarker and potential target for treatment of gliomas." (PMID 33292262, 2020). "Additionally, SLC39A1 might influence immune cell infiltration in the glioma TME." (PMID 37298344, 2023). "Meanwhile, the glioma patients with higher PTBP1, SLC39A1, MMP9, and SLC16A3 expression had shorter OS (p < 0.01)." (PMID 36307882, 2022). "Furthermore, correlation analysis has showed that the expression level of SLC39A1 is significantly correlated with PRS type, histology, grade, age, chemo status, IDH mutation status, and 1p19q codeletion status, suggesting that SLC39A1 may be related to glioma progression." (PMID 33292262, 2020). "In addition, SLC39A1 may affect the infiltration of immune cells in the glioma microenvironment." (PMID 33292262, 2020). "SLC39A1 could foster the MMP2/MMP9 expression and glioma cell proliferation and its expression is correlated to the pathological grade, IDH mutational status, and 1p19q co-deletion." (PMID 39012280, 2024). "In addition, correlation analysis indicates that SLC39A1 is highly correlated with MMP2\MMP9, suggesting that the up-regulated expression of SLC39A1 may promote the progression of glioma by increasing the intake of zinc ions and increasing the expression level of MMP2\MMP9." (PMID 33292262, 2020).
gastric cancer (6 papers, 2015 to 2022). A primary or metastatic malignant neoplasm involving the stomach. "SLC39A1 triggered significant alteration in genes related to urinary system and kidney disease, lung disease, atherosclerosis, and stomach cancer." (PMID 36407113, 2022). "Consistent with its dysregulation in gastric cancer, a previous study reported that SLC39A1 was significantly upregulated in breast cancer tissues compared with normal breast tissues." (PMID 36407082, 2022). "The tumor-related role of SLC39A1 in gastric cancer was finally proven through in vitro and in vivo experiments." (PMID 36407082, 2022). "According to the transcripts per million (TPM), gastric cancer tissues possessed significantly higher SLC39A1-mRNA level than normal stomach tissues (P < 0.001)." (PMID 36407082, 2022). "Here, we demonstrated that SLC39A1 was upregulated in gastric cancer tissues, and its hyper-expression was correlated with unfavorable prognosis." (PMID 36407082, 2022). "Since clinical data analyses emphasized the potential involvement of SLC39A1 in gastric cancer, we were engaged to dig into its detailed effects using in vitro cell lines, including MKN28 cells and MKN45 cells." (PMID 36407082, 2022). "To further confirm the tumor-related role of SLC39A1 in gastric cancer, we finally conducted in vivo experiments using nude mice models." (PMID 36407082, 2022). "In vitro and in vivo assays demonstrated that overexpressing SLC39A1 could promote gastric cancer growth and invasion, while silencing SLC39A1 led to opposite effects." (PMID 36407082, 2022). "Higher expression of SLC39A1, 5–7, and 9 indicated better OS, FPS, and PPS, and increased SLC39A2–4, 8, and SLC39A10 expression indicated poor OS, FP, and PPS in the patients with gastric cancer." (PMID 34925450, 2021).
hepatocellular carcinoma (6 papers, 2013 to 2025). A malignant tumor that arises from hepatocytes. "On the contrary, a study using an early‐stage hepatocellular carcinoma (EHCC) cohort indicates that tumour tissues exhibit decreased expression of SLC39A1 as compared with the adjacent tissues." (PMID 40462487, 2025). "However, in our current research, we found that SLC39A1 might be a potential tumor suppressor in hepatocellular carcinoma." (PMID 34615436, 2021). "However, the clinical impacts of SLC39A1 in early-stage hepatocellular carcinoma (EHCC) have not been defined." (PMID 34615436, 2021).
breast carcinoma (4 papers, 2016 to 2022). "Among these genes, ZNHIT6 and SLC39A1 have been linked to prostate or breast cancer." (PMID 26951498, 2016).
Obesity (4 papers, 2017 to 2022). Accumulation of substantial excess body fat. "These candidates were further refined by searching for genes that have been implicated in NAFLD genome-wide association studies (Ppp1ca), genes associated with other liver disease, (Dguok, Ass1), and obesity-related genes (Slc39a1)." (PMID 29847571, 2018).